MYRIP (myosin VIIA and Rab interacting protein)
Description:
Rab effector protein involved in melanosome transport. Serves as link between melanosome-bound RAB27A and the motor proteins MYO5A and MYO7A. May link RAB27A-containing vesicles to actin filaments. Functions as a protein kinase A-anchoring protein (AKAP). May act as a scaffolding protein that links PKA to components of the exocytosis machinery, thus facilitating exocytosis, including insulin release (By similarity).
Synonyms: SlaC2-c; SLAC2C; DKFZp586F1018; exophilin-8
Tractability: No criterion of Open Targets' tractability assessment is met for any kind of drug.
Gene: Protein-coding gene on chromosome 3 (39,808,914 to 40,260,321, forward strand). Ensembl gene ENSG00000170011.
Subcellular location: Cytoplasm; Cytoplasm, perinuclear region; Cytoplasmic vesicle, secretory vesicle
Subcellular location (Human Protein Atlas): Golgi apparatus; Nucleoli fibrillar center; Nucleoplasm
Pathways (Reactome):
Developmental Biology: Regulation of MITF-M-dependent genes involved in pigmentation
Metabolism of proteins: Insulin processing
Gene Ontology:
Molecular function: protein binding; actin binding; myosin binding; zinc ion binding; protein kinase A binding; small GTPase binding
Biological process: positive regulation of insulin secretion; intracellular protein transport
Cellular component: cortical actin cytoskeleton; cytosol; dense core granule; perinuclear region of cytoplasm; actin cytoskeleton; cytoplasm; exocyst; melanosome; photoreceptor outer segment; synapse; transport vesicle
Genetic constraint (gnomAD): Loss-of-function variants: 46 observed, 92.45 expected, observed/expected ratio (o/e) 0.5, 90% interval 0.39 to 0.64. The upper end of that interval is the gene's LOEUF score, 0.64, which puts it in group 2 of 6, group 1 being the genes least tolerant of losing a copy. Missense variants: 957 observed, 1,055.7 expected, observed/expected ratio (o/e) 0.91, 90% interval 0.86 to 0.96. Synonymous variants: 386 observed, 410.13 expected, observed/expected ratio (o/e) 0.94, 90% interval 0.87 to 1.02.
Homologues: Orthologues: macaque MYRIP (97% identical), chimpanzee MYRIP (93% identical), pig MYRIP (86% identical), rabbit MYRIP (81% identical), mouse Myrip (80% identical), rat Myrip (79% identical), guinea pig MYRIP (72% identical), tropical clawed frog myrip (62% identical), zebrafish myripb (45% identical), zebrafish myripa (41% identical). Paralogues in human: MLPH (19% identical), MOBP (8% identical).
Diseases named in the same sentence as MYRIP in open-access papers:
MYRIP is named in the same sentence as 12 diseases in open-access papers, as found by Europe PMC text mining. Sharing a sentence is not in itself a finding about the gene and the disease. The quoted sentences say what the papers report.
age-related macular degeneration (1 paper, 2024). Age-related loss of vision in the central portion of the retina (macula), secondary to retinal degeneration. "Previous GWAS research has demonstrated that variants in the MYRIP gene have been implicated in age-related macular degeneration and cognitive function, which was consistent with its protective role in AD." (PMID 39559883, 2024).
Alzheimer disease (1 paper, 2019). A progressive, neurodegenerative disease characterized by loss of function and death of nerve cells in several areas of the brain leading to loss of cognitive function such as memory and language. "The 18th SNP resides in gene MYRIP, which is also repoted to be related with Alzheimer’s disease." (PMID 31881907, 2019).
cardiac hypertrophy (1 paper, 2021). "In particular, MYRIP was associated with cardiac hypertrophy signaling (e.g., NFAT pathway, NPPA, and NPPB) and aldosterone signaling." (PMID 33679876, 2021). "Differential expression analysis of MYRIP knockdowns compared to the control identified changes in expression of cardiac hypertrophy pathways." (PMID 33679876, 2021).
depression (1 paper, 2021). "The MYRIP gene is also reported to have a role in insulin secretion and low insulin levels have been linked to depression." (PMID 35069690, 2021).
heart failure (1 paper, 2021). Inability of the heart to pump blood at an adequate rate to meet tissue metabolic requirements. "Finally, based on gene expression, there was a very significant predicted decrease in the regulation of the oxidative phosphorylation pathway in MYRIP knockdowns, suggesting a state of relative energy deprivation characteristic of LVH and heart failure." (PMID 33679876, 2021).
skin (2 papers, 2022 to 2023). "The upregulation of MyRIP may be related to skin hyperpigmentation in severe patients." (PMID 35953823, 2022).
cancer (1 paper, 2024). A tumor composed of atypical neoplastic, often pleomorphic cells that invade other tissues. "Among the downregulated DEGs, PLEKHA5, GRK4, MYRIP, and CD40 have established associations with various human cancers." (PMID 39911484, 2024).
MYRIP also shares sentences with these, for which no sentence is quoted: Hypertension (2 papers); Glucose intolerance (1); hepatocellular carcinoma (1); left ventricular hypertrophy (1); melanoma (1).